H3C11 (H3 clustered histone 11)
Description:
Core component of nucleosome. Nucleosomes wrap and compact DNA into chromatin, limiting DNA accessibility to the cellular machineries which require DNA as a template. Histones thereby play a central role in transcription regulation, DNA repair, DNA replication and chromosomal stability. DNA accessibility is regulated via a complex set of post-translational modifications of histones, also called histone code, and nucleosome remodeling.
Synonyms: H3FF; HIST1H3I; H3/f; H3.f
Gene: Protein-coding gene on chromosome 6 (27,871,845 to 27,872,346, reverse strand). Ensembl gene ENSG00000275379.
Subcellular location: Nucleus; Chromosome
Subcellular location (Human Protein Atlas): Nucleoplasm
Pathways (Reactome):
Gene expression (Transcription): B-WICH complex positively regulates rRNA expression; DNA methylation; ERCC6 (CSB) and EHMT2 (G9a) positively regulate rRNA expression; MLL4 and MLL3 complexes regulate expression of PPARG target genes in adipogenesis and hepatic steatosis; NoRC negatively regulates rRNA expression; PRC2 methylates histones and DNA; RNA Polymerase I Promoter Escape; RNA Polymerase I Promoter Opening; RUNX1 regulates genes involved in megakaryocyte differentiation and platelet function; RUNX1 regulates transcription of genes involved in differentiation of HSCs; Regulation of endogenous retroelements by KRAB-ZFP proteins; Regulation of endogenous retroelements by Piwi-interacting RNAs (piRNAs); Regulation of endogenous retroelements by the Human Silencing Hub (HUSH) complex; SIRT1 negatively regulates rRNA expression; Transcriptional regulation by small RNAs
Chromatin organization: CHD1 and CHD2 subfamily; CHD6, CHD7, CHD8, CHD9 subfamily; ChAHP complex assembly; Chromatin modifying enzymes; HATs acetylate histones; HDACs deacetylate histones; HDMs demethylate histones; Interaction of NuRD complexes with transcription factors; NuRD complex assembly; PKMTs methylate histone lysines; RMTs methylate histone arginines
Disease: Defective pyroptosis; Dengue Virus-Host Interactions; HCMV Early Events; HCMV Late Events
Signal Transduction: Activated PKN1 stimulates transcription of AR (androgen receptor) regulated genes KLK2 and KLK3; Estrogen-dependent gene expression; Formation of the beta-catenin:TCF transactivating complex; Pre-NOTCH Transcription and Translation
Developmental Biology: Activation of anterior HOX genes in hindbrain development during early embryogenesis; Chromatin modifications during the maternal to zygotic transition (MZT); Transcriptional regulation of granulopoiesis
Immune System: FXIIa activates plasma kallikrein-kinin system; Interleukin-7 signaling; Regulation of PD-L1(CD274) transcription
and 8 more pathways
Gene Ontology:
Molecular function: cadherin binding; protein binding; structural constituent of chromatin; nucleosomal DNA binding; DNA binding; protein heterodimerization activity
Biological process: epigenetic regulation of gene expression; nucleosome assembly; chromatin organization; heterochromatin formation; telomere organization
Cellular component: chromatin; extracellular exosome; membrane; nucleoplasm; nucleosome; nucleus; protein-containing complex; extracellular region; chromosome
Genetic constraint (gnomAD): Loss-of-function variants: 10 observed, 9.94 expected, observed/expected ratio (o/e) 1.01, 90% interval 0.62 to 1.66. That is too few expected variants to judge how well the gene tolerates losing a copy. Missense variants: 197 observed, 207.5 expected, observed/expected ratio (o/e) 0.95, 90% interval 0.84 to 1.07. Synonymous variants: 132 observed, 88.49 expected, observed/expected ratio (o/e) 1.49, 90% interval 1.29 to 1.72.
Homologues: Orthologues: Drosophila melanogaster His3:CG33812 (99% identical), zebrafish si:ch1073-153i20.2 (99% identical), zebrafish si:ch211-113a14.20 (99% identical), zebrafish si:ch211-113a14.23 (99% identical), zebrafish si:ch211-113a14.27 (99% identical), zebrafish zgc:173552 (99% identical), Caenorhabditis elegans his-17 (97% identical), Caenorhabditis elegans his-2 (97% identical), Caenorhabditis elegans his-32 (97% identical), Caenorhabditis elegans his-40 (97% identical), Caenorhabditis elegans his-42 (97% identical), Caenorhabditis elegans his-45 (97% identical), and 5 more. Paralogues in human: H3C1 (100% identical), H3C10 (100% identical), H3C12 (100% identical), H3C2 (100% identical), H3C3 (100% identical), H3C4 (100% identical), H3C6 (100% identical), H3C7 (100% identical), H3C8 (100% identical), H3C13 (99% identical), H3C14 (99% identical), H3C15 (99% identical), and 8 more.
Diseases named in the same sentence as H3C11 in open-access papers:
H3C11 is named in the same sentence as 1 disease in open-access papers, as found by Europe PMC text mining. Sharing a sentence is not in itself a finding about the gene and the disease.
H3C11 shares sentences with these, for which no sentence is quoted: systemic lupus erythematosus (1 paper).